UCP1 (uncoupling protein 1)
Diseases named in the same sentence as UCP1 in open-access papers (continued):
Sharing a sentence is not in itself a finding about the gene and the disease.
Obesity (continued). "Studies have demonstrated that browning of WAT with increased UCP1 expression exerts anti-obesity effects in rodent models." (PMID 34646848, 2021). "We used female mice in this study, as several studies, including our previous aging study, reported that females were more dependent on UCP1 thermogenesis than males for maintaining body temperature in the cold and avoiding obesity with age." (PMID 33525404, 2021). "A transgenic mouse overexpressing UCP1 has resistance to obesity development and polymorphisms in UCP genes in children have been associated with obesity." (PMID 33800718, 2021). "We also sought to determine if the AGE/RAGE/DIAPH1 axis is linked to markers of adipogenesis (PPARG & PPARGC1A) and metabolic genes that we previously identified to be regulated by RAGE in a mouse model of obesity (UCP1 and CIDEA)." (PMID 34103691, 2021). "It is generally accepted that BAT thermogenesis is primarily mediated by the action of mitochondrial uncoupling protein 1 (UCP1) to protect against obesity and diabetes, which is a major focus in human obesity research." (PMID 34576181, 2021). "In this same study, the authors demonstrated that when Ucp1 knockout mice were housed at thermoneutral temperature (i.e., 30 °C), they do indeed develop obesity even when fed standard diet." (PMID 34829617, 2021). "The brown and the beige adipocytes contain numerous mitochondria and express the uncoupling protein 1 (UCP-1), which regulates energy expenditure, reduces adiposity, and protects experimental animals from diet-induced obesity." (PMID 33557185, 2021). "Subsequent studies reported dysregulated BAT function in other models of obesity, while genetic disruption of UCP1 induced obesity in mice at thermoneutrality as did ablation of BAT." (PMID 34063868, 2021). "Selenation of Ucp1 increases its redox sensitivity, enhancing energy expenditure, activating adaptive thermogenic responses, and protecting from high-fat diet-induced obesity." (PMID 33435397, 2021). "The expectations that UCP1 could play a protective role in CV health were based on the collected experimental evidence and epidemiological reports, which demonstrated an inverse association between UCP1 transcription and insulin resistance, dyslipidemia and obesity." (PMID 34067093, 2021). "S2B), suggesting that obesity-induced endothelial dysfunction is at least partially mediated by PVAT and is further exacerbated by UCP1 deficiency within PVAT." (PMID 34878840, 2021). "Further evidence for the UCP1 antidiabetic and anti-obesity effect comes from studies in transgenic mice models overexpressing UCP1." (PMID 34829617, 2021). "In fact, by consuming too many nutrients and being exposed to cold temperatures, UCP1 is expressed to protect the body’s organisms against obesity and the cold." (PMID 33924341, 2021). "Brown adipose tissue (BAT) plays an important role in thermogenic regulation, which contributes to alleviating diet-induced obesity through uncoupling protein 1 (UCP1) expression." (PMID 34501754, 2021). "Previous studies have revealed that BAT dissipates excessive energy into heat via UCP-1 and protects against obesity and its related disorders." (PMID 34222665, 2021). "In accordance with these results, more recent studies have also described the obesogenic role of Ucp1 ablation in mice kept at ~30 °C, even for notoriously obesity resistant 129 mice strain." (PMID 34829617, 2021). "Taken together, these results indicate that GD improves visceral adiposity by upregulating UCP1 expression, providing a novel perspective on combating obesity." (PMID 34646848, 2021). "Uncoupling protein-1 (UCP1) is a thermogenetic-related gene expressed in brown adipose tissue, which can disperse energy as heat to fight obesity." (PMID 34444752, 2021). "Mice fed with a high-fat diet (HFD) were protected from obesity and related metabolic disorders when given IL-25 through a process that involved the uncoupling protein 1 (UCP1)-mediated thermogenesis." (PMID 34351905, 2021).
Obesity (continued). "Studies have demonstrated that the browning process accompanied by increased Ucp1 expression exerts anti-obesity effects in rodent models." (PMID 34646848, 2021). "UCP1 is even considered to be a key factor in many metabolic diseases such as diabetes and obesity 10-12." (PMID 33754018, 2021). "This anti-obesity effect was mediated by the increased O2 consumption, CO2 production, and energy expenditure, which was further evidenced by the upregulation of uncoupling protein-1 (UCP-1) and metabolism-associated genes." (PMID 34222665, 2021). "Utilizing transgenic animals, several studies have demonstrated the anti-obesity and insulin sensitizing effects in adipocytes and skeletal muscle with UCP1 overexpression." (PMID 34829779, 2021). "Genetic removal of Ucp1 in mice promotes obesity and insulin resistance when mice are fed a diet high in fat and housed under thermoneutral conditions (29–30 °C), indicating a vital role for this protein in diet-induced thermogenesis." (PMID 34453052, 2021). "Intriguingly, Ucp1 KO mice fed a high-fat diet (HFD) were resistant to the development of obesity at room temperature, suggesting the activation of a UCP1-independent thermogenic pathway." (PMID 32849287, 2020). "Upon the inhibition of CK2 in vivo, the authors observed a rise in energy expenditure, as well as alleviation of HFD-induced obesity and insulin resistance via the induction of UCP1-mediated thermogenesis." (PMID 32174890, 2020). "Engraftment of mast cell-deficient mice with Tph1−/− mast cells or selective mast cell deletion of Tph1 enhances uncoupling protein 1 (Ucp1) expression in white adipose tissue and protects mice from developing obesity and insulin resistance." (PMID 31974364, 2020). "As in the case of constitutive deletion of ERK3 in the adipocytes, induction of ERK3 removal in mice with established obesity resulted in elevated expression of Ucp1 and other thermogenic genes in subWAT and BAT." (PMID 32139423, 2020). "UCP1 plays a clear role in energy expenditure and obesity, and UCP1 overexpression in adipose tissue protects against diet-induced obesity." (PMID 32713230, 2020). "Taken together, the global transcriptomic analyses exclude BAT as contributing organ to the development of obesity resistance in UCP1 KO mice and highlights iWAT remodeling as driving force." (PMID 32005798, 2020). "In contrast, when housed at thermoneutrality, Ucp1 knockout mice have increased sensitivity to diet-induced obesity." (PMID 32256446, 2020). "This suggests that by decreasing the expression of Pgc-1α, Prdm16 and Cidea, DBP exposure reduced the levels of UCP1 and lipid degradation and accelerated the accumulation of fat, thus resulting in obesity." (PMID 33004990, 2020). "Beige fat expressing UCP1 provides a defence against cold and obesity, and tyrosine hydroxylase is required for the development of beige fat37." (PMID 32686763, 2020). "A previous study reported that pharmacological activation of AMPK promotes beiging in iWAT, with a concomitant increase in UCP1 protein expression, and a modest protection against high-fat diet-induced obesity." (PMID 32539124, 2020). "Uncoupling protein 1 (UCP1) is implicated in thermogenesis, energy expenditure, and reduction of oxidative stress that associated with the progress of obesity and diabetes mellitus type 2 (DM2)." (PMID 32197395, 2020). "Brown adipose thermogenesis increases energy expenditure and relies on uncoupling protein 1 (UCP1), however, UCP1 knock-out mice show resistance to diet-induced obesity at room temperature." (PMID 32005798, 2020). "The knockout mouse of thermogenic UCP1 provides probably the most extensively studied animal model to investigate anti-obesity mechanisms mediated by BAT." (PMID 32005798, 2020). "Thermogenic brown and beige adipocytes oxidize metabolic substrates producing heat, mainly by the mitochondrial uncoupling protein UCP1, and can thus counteract obesity." (PMID 32927882, 2020).
Obesity (continued). "High fat diet-fed adipocyte-specific ASK1 knockout mice reveal increased UCP1 protein levels in inguinal adipose tissue concomitant with elevated energy expenditure, reduced obesity and ameliorated glucose tolerance compared to control littermates." (PMID 32242025, 2020). "Neither the regulation nor the underlying molecular mechanisms have been understood yet, labeling the observation as ‘paradoxical resistance to diet-induced obesity of high fat diet fed UCP1 KO mice’23." (PMID 32005798, 2020). "The activation of the uncoupling protein (UCP1–3) in the mitochondria elicits anti-obesity effects by enhancing thermogenesis that converts the energy obtained from foods to heat rather than fat." (PMID 35494723, 2020). "UCP1-null mice display intolerant to cold and develop obesity housed at a thermoneutral temperature." (PMID 32190098, 2020). "The genes CKMT1A and CKMT1B, which encode key mitochondrial creatine kinases and reported to be involved in UCP1-independent thermogenesis, were among those being significantly less expressed in FTO obesity-risk samples." (PMID 32316277, 2020). "The UCP1/FGF21 dKO mouse unambiguously pinpoints endogenous FGF21 as primary crucial mediator of obesity resistance, and iWAT as the target organ." (PMID 32005798, 2020). "Although the UCP1-knockout (UCP1 KO) mouse represents the most frequently applied animal model to judge the anti-obesity effects of UCP1, the assessment is confounded by unknown anti-obesity factors causing paradoxical obesity resistance below thermoneutral temperatures." (PMID 32005798, 2020). "Uncoupling of the mitochondrial respiratory chain by UCP1 serves to increase heat production during cold exposure, particularly in hairless neonates, and provides resistance to obesity resulting from overfeeding." (PMID 32539124, 2020). "The discovery of UCP1-independent thermogenic mechanisms potential offer new opportunities for improving obesity and type 2 diabetes particularly in groups such as elderly and obese populations who do not possess UCP1 positive adipocytes." (PMID 32849287, 2020). "Increased expression levels of PGC-1α and UCP1 have also been detected in mouse models of obesity that have been treated with the SGLT2 inhibitors Canagliflozin and Empagliflozin, respectively." (PMID 33218034, 2020). "UCP1 ablation induced obesity in mice fed a normal diet and vastly augmented high-fat diet-induced obesity in C57Bl6 mice that were exempt from thermal stress by living in a thermogenically non-recruited state." (PMID 33271769, 2020). "In HFD-fed mice, GA treatment protects diet-induced obesity, improves glucose and insulin homeostasis, and promotes thermogenesis by increasing uncoupling protein 1 (UCP1) expression in brown adipose tissue." (PMID 33036205, 2020). "The abnormal expression of Pgc-1αand UCP1 in brown fat cells appears to be involved in the generation of obesity." (PMID 33004990, 2020). "It should be mentioned that associations of genetic variants in UCP1 and LEP with obesity have further been replicated in cohorts of Asian ancestry." (PMID 33193685, 2020). "Increasing UCP1 activity has also been shown to protect against obesity in aP2-Ucp transgenic genetically obese agouti viable yellow mice and reduce subcutaneous fat in aP2-Ucp C57BL/6J mice." (PMID 31220223, 2020). "Brown adipose tissue generates heat via the mitochondrial uncoupling protein UCP1 to protect against obesity and hypothermia." (PMID 32686763, 2020). "Whereas, ILC-2 isolated from murine and human white adipose tissue (WAT) when activated can promote beiging of WAT and induction of uncoupling protein 1 (UCP1) to limit the development of obesity." (PMID 32881912, 2020). "While our findings highlight an interesting regulation of Clstn3β in conditions associated with BAT dysfunction, this calls for further investigation about the complex interplay between Clstn3β, S100b and Ucp1 in BAT in the context of obesity." (PMID 33101212, 2020).
Obesity (continued). "The possibility of Ucp1 activation in white adipose tissue, including the use of irisin, is considered as one of the strategies to combat obesity and thus to fight against T2D and cardiovascular disorders." (PMID 32450815, 2020). "Intrauterine exposure of mice to low-dose DBP appears to promote obesity in offspring by inhibiting UCP1 via ER stress, a process that was largely reversed by treatment with TUDCA." (PMID 33004990, 2020). "Recently, brown adipose tissue has been in the focus of metabolism research, which can dissipate energy by the regulation of uncoupling protein-1, increase fatty acid oxidation and heat production and counteract obesity." (PMID 32046629, 2020). "Consistent with known and expected phenotypes of ob/ob mice, we observed severe obesity, tissue adiposity and glucose intolerance in ob/ob mice, with significantly decreased UCP1 level in BAT." (PMID 32698539, 2020). "Since the Ucp1 induction in adipocytes can enhance energy expenditure and prevent obesity and metabolic diseases in diet-induced obese mice, we investigated the effect of sesamol on energy expenditure." (PMID 32443555, 2020). "Of note, an animal model of genetic obesity using adipose tissue-targeted overexpression of UCP1 resulted in a reduced level of obesity." (PMID 32717874, 2020). "Because of the increased energy cost to activate alternative forms of adaptive thermogenesis, Ucp1 knockout mice are resistant to diet-induced obesity when housed at room temperature." (PMID 32256446, 2020). "Evidently, such data are important to allow for possible translation of UCP1 effects to human conditions, as metabolic effects of UCP1 restricted to a single obesity-prone mouse strain would hardly be transferable to humans." (PMID 30807213, 2019). "Fucoxanthin anti-obesity activity has been attributed to the stimulation of thermogenesis by increasing the expression of uncoupling protein 1 (UCP1) in adipose tissues as well as to effects on intestinal lipid absorption and lipid metabolism." (PMID 30959933, 2019). "These beige adipocytes resemble classical brown adipocytes with high UCP1 expression; therefore, it is suggested that their generation increases energy expenditure and can prevent obesity." (PMID 31847296, 2019). "Moreover, it has been suggested in animal studies that it is the UCP1+ cell ablation or the Ucp1 mutation of brown fat cells overall that has a beneficial effect in preventing obesity and diabetes, however the contribution of each type of brown cell to this process remains unclear." (PMID 31428053, 2019). "By demonstrating the significance of UCP1 in a mouse strain that is so markedly metabolically opposite of the obesity-prone C57Bl/6 mouse strain, we infer here that BAT and UCP1 are of metabolic significance principally in all mouse strains." (PMID 30807213, 2019). "Due to their ability to dissipate energy as heat and ameliorate metabolic disorders, UCP1-expressing adipocytes are considered as a potential target for anti-obesity treatment." (PMID 31730675, 2019). "Treatment with the general cyclooxygenase inhibitor indomethacin accentuated HFD-induced obesity in the obesity resistant Sv129 mice and reduced diet-induced expression of UCP1 in iWAT1,8,9." (PMID 31222118, 2019). "The development of obesity induced by the ablation of UCP1 progressively worsens, as the gap between the UCP1 amount that the animal should have, but lacks, widens." (PMID 30807213, 2019). "It is well known that increased expression of UCP1 in brown adipocyte or ectopic expression of UCP1 in mouse or human skeletal muscle and white adipocyte promotes fatty acid oxidation and resistance to obesity." (PMID 31842884, 2019). "Although this tenet had already been implied in 1979 by Rothwell and Stock, direct experimental evidence for a significant role for UCP1 in counteracting obesity has been limited to the metabolic consequences of ablation of UCP1." (PMID 30807213, 2019).
Obesity (continued). "The reported phenotype is fundamentally different to the phenotype described here and includes a decrease in thermogenic capacity of the adipose tissue, as a result of downregulation of UCP1 and consequent development of obesity and liver steatosis." (PMID 30948720, 2019). "While cold is the main stimulus for UCP1 increases in BAT, diet-induced obesity also increases BAT UCP1." (PMID 30804793, 2019). "Recently, the anti-obesity effect of FX was found to involve stimulation of the uncoupling protein-1 (UCP1) expression in white adipose tissue (WAT)." (PMID 31137922, 2019). "EHMT1 increases the production of UCP1, and the deletion of this EHMT1 causes insulin resistance and obesity in mice, while a haploinsuffiency is related to obesity and insulin resistance in humans." (PMID 31614705, 2019). "To determine the metabolic significance of UCP1 in the obesity-resistant 129S2/sv mice, we examined the effects of UCP1 ablation on body composition and energy metabolism." (PMID 30807213, 2019). "To exclude that the importance of UCP1 for body weight regulation in obesity-resistant mice is restricted to the 129S2/sv substrain, we performed a similar experiment on 129SV/pas mice." (PMID 30807213, 2019). "In the present investigation, we demonstrate that the obesity-reducing effect of UCP1 is observable not only in an obesity-prone mouse strain but also in mouse strains that are recognized to be obesity resistant." (PMID 30807213, 2019). "In our study, the anti-obesity effect of PE was evaluated in thermogenesis by examining UCP1 induction and lipolysis-related genes." (PMID 31137922, 2019). "Ucp1 null mice develop obesity, while the overexpression of Ucp1 in mice results in protection from diet-induced obesity." (PMID 31312229, 2019). "Recently, the Kajimura group demonstrated that the β3-adrenergic receptor (β3-AR) agonist treatment of UCP1+ adipocyte-specific autophagy-null mice enhanced beige adipocyte maintenance and attenuated diet-induced obesity." (PMID 31323770, 2019). "Clearly, it is thus of importance to examine to which degree the obesity-inducing effect of UCP1 ablation is a phenomenon also observable in strains that do not readily become obese." (PMID 30807213, 2019). "Given the ability of uncoupled respiration mediated by BAT and UCP1 to dispense of excess caloric intake as heat, there has long been a desire to harness this effect to oppose obesity and metabolic syndrome." (PMID 31370146, 2019). "WAT primarily stores lipids, and BAT confers anti-obesity effects by metabolizing lipids through uncoupling protein 1 (UCP1)-mediated uncoupled respiration." (PMID 31667363, 2019). "In an attempt to promote beige adipocytes in obesity, IL-33-elicited ILC2s were transferred and led to increased uncoupling protein 1 (UCP1) beige adipocytes, a process that regulates caloric expenditure." (PMID 31191541, 2019). "In the UCP1 overexpressing transgenic mouse model, mice were resistant to obesity induced by a high-fat diet." (PMID 31365569, 2019). "This increase in UCP1 expression increases energy expenditure and thus is helpful for improving obesity." (PMID 31137922, 2019). "We find here and earlier that in mice there is a positive relationship between obesity and UCP1 and BAT amounts, and there are similar indications in humans." (PMID 30807213, 2019). "On the other hand, some recent studies have reported that organo-sulfur compounds can ameliorate obesity by enhancing uncoupling protein 1 expression, glucose uptake, oxidative utilization, lipolysis, and fatty oxidation in 3T3-L1 adipocytes." (PMID 31547031, 2019). "We analyzed determinants of REE in patients with obesity and assessed UCP1 expression as a “brite” marker in abdominal subcutaneous AT (SAT) and visceral omental AT (VAT)." (PMID 31440209, 2019). "Our results clearly showed that UCP1-VAT expression was significantly increased in severe human obesity (BMI > 50 kg/m2) and that it behaved as an independent predictor of REE." (PMID 31440209, 2019).